TRIM43B (tripartite motif containing 43B)
Tractability: No criterion of Open Targets' tractability assessment is met for any kind of drug.
Gene: Protein-coding gene on chromosome 2 (95,477,008 to 95,484,754, reverse strand). Ensembl gene ENSG00000144010.
Gene Ontology:
Molecular function: ubiquitin protein ligase activity; zinc ion binding
Biological process: innate immune response; regulation of gene expression
Cellular component: cytoplasm
Genetic constraint (gnomAD): Loss-of-function variants: 15 observed, 25.09 expected, observed/expected ratio (o/e) 0.6, 90% interval 0.4 to 0.92. The upper end of that interval is the gene's LOEUF score, 0.92, which puts it in group 3 of 6, group 1 being the genes least tolerant of losing a copy. Missense variants: 172 observed, 271.31 expected, observed/expected ratio (o/e) 0.63, 90% interval 0.56 to 0.72. Synonymous variants: 69 observed, 88.1 expected, observed/expected ratio (o/e) 0.78, 90% interval 0.64 to 0.96.
Homologues: Orthologues: rat Trim43a (47% identical), mouse Trim43c (42% identical), mouse Trim43a (41% identical), mouse Trim43b (41% identical). Paralogues in human: TRIM43 (99% identical), TRIM49C (52% identical), TRIM49 (52% identical), TRIM49B (52% identical), TRIM51 (51% identical), TRIM49D1 (51% identical), TRIM49D2 (51% identical), TRIM51G (49% identical), TRIM64 (48% identical), TRIM77 (48% identical), TRIM64B (48% identical), TRIM64C (47% identical), and 68 more.